CD28 (CD28 molecule)
Diseases named in the same sentence as CD28 in open-access papers (continued):
Sharing a sentence is not in itself a finding about the gene and the disease.
cancer (continued). "In a clinical trial, patients with cancer with NSCLC who received oral calcitriol (1α,25(OH)2D3) showed decreased cell-surface level of PD-1, Tim-3 and TIGIT and increased CD28 expression on Vγ9Vδ2+ and CD8+ T cells." (PMID 35318258, 2022). "The results revealed that CD45 was positively correlated with the expression levels of genes characteristic of exhausted T cells across cancers, such as CXCL9, IL10, CD28, IDO1 and CCR4." (PMID 36061172, 2022). "Other immune checkpoint-related genes as CD28, TGFBR1, and TNFSF4 (OX40L) have been frequently reported to engage in cancer immune regulation in ICI research." (PMID 34897033, 2021). "The results showed that the five TLR4 prognosis-related cancers KIRC, SKCM, STAD, TGCT, and UCEC were related to ICOS, CTLA4, CD28, and CD80." (PMID 34631699, 2021). "In cancer immunotherapy, CAR T cells are expanded with CD3 and CD28 stimulation for a few weeks before in vivo transfer." (PMID 33752225, 2021). "Additional engineering of CAR T-cells to include intracellular signaling motifs from costimulatory molecules such as CD28, 4-1BB, OX40, and ICOS serve to enhance their proliferation and ability to eradicate cancer cells and cytokine production." (PMID 33442419, 2021). "T cells can be engineered to express chimeric antigen receptors (CARs) that specifically target antigens on the surface of cancer cells, and signal through protein elements derived from both the TCR and CD28 or other co-stimulatory receptors." (PMID 34970966, 2021). "We also noted reduced surface expressions of CD62L, CD28, CCR7, and CD127 on cancer patients’ T cells." (PMID 33230147, 2020). "CD86 (B7-2), one of the checkpoint proteins in antigen-presenting cells (APCs), interacts with CD28 and cytotoxic T lymphocyte antigen‐4 (CTLA‐4) receptors on T cells, thereby limiting T-cell activation and inducing immunoescape of cancers." (PMID 33425732, 2020). "Recently, several studies have described relationships among TLRs, CD14, CD25, CD28, and CD61 and the evolution of human cancers." (PMID 31523179, 2019). "Ten healthy adults and 45 cancer patients were analyzed for gene expression of PD-1, CTLA-4, CD25, CD28, IL-10, TGF-β and Foxp3 in peripheral blood." (PMID 28881603, 2017). "While CD28 promoted better control over HIV in vitro compared to 4-1BB, discrepancies between the in vitro and in vivo activity of cancer-specific CARs containing 4-1BB had been reported." (PMID 29023549, 2017). "Gene expression of PD-1 as well as CTLA-4, CD25, CD28, Foxp3, TGF-β and IL-10 was increased in most cancer patients compared to that in healthy adults." (PMID 28881603, 2017). "For LH-type diabodies, the expression vectors of anti-cancer VH domain were first produced and the anti-CD3 or –CD28 VL genes were simultaneously ligated into the linearized vectors of anti-cancer VH domain." (PMID 28588218, 2017). "An active role in the immune surveillance mechanisms of CD8+ lymphocytes expressing CD28, the CD80 receptor essential for T cell activation, is supported by their diminished number at the cancer stage in patients with UC." (PMID 25595911, 2015). "The inverse observation was made for CD28+CD57- cells, harbouring the naïve and central memory cell populations, with lower proportions among the cancer patients, resulting mainly from the lower values among stage IV patients." (PMID 26711627, 2015). "Changes in CD8+ T-cell subsets, based on the expression of CD28 and CD57, were analysed in patients with various forms of cancer affecting the lungs, undergoing chemotherapy and in a control group over six months, using multi-colour flow cytometry." (PMID 26711627, 2015). "Complementing the accumulation of CD28-CD57+ cells and the decline in CD28+CD57- cells, a decreased ratio of CD8- to CD8+ cells was observed among the cancer patients compared to the controls." (PMID 26711627, 2015).
cancer (continued). "The CD28 signaling pathway and its metabolic profile are important factors contributing to the poor persistence of CD28-based CAR-T cells in vivo, which often leads to cancer recurrence." (PMID 40181986, 2025). "Despite early interest in harnessing costimulation as a cancer immunotherapy, to date, no drugs targeting CD28 have received regulatory approval." (PMID 39301613, 2025). "After activation and expansion of epitope specific memory CD8+ T cells (effector cells) through peptide mixture and anti-CD28 antibody, we first detected the effects of cytotoxic CD8+ T cells on the 4T1-turbo cell line by using an optimal ratio of target cancer cells to effector cells (4-5:1)." (PMID 41050655, 2025). "On the other hand, CD28 in cancer cells (not T cells) promotes immune escape rather than immune activation." (PMID 41155258, 2025). "After 12 days of culture, consistent with numerous in vitro Vδ2 T cell expansion protocols for cancer therapy, we assessed the proliferation and cytokine production capacity of Vδ2 T cells by flow cytometry upon anti‐CD3 and anti‐CD28 restimulation." (PMID 40264329, 2025). "More recent research has linked ICOS to the functional advantage of CD8+ antigen-specific T-cell clones isolated from melanoma patients through activation of AKT in the absence of CD28, suggesting a potential role in cancer immunotherapy." (PMID 39684559, 2024). "Therefore, a sensitive balance exists between levels of CD28 and CTLA-4 expression in T cells, bringing the final decision to either attack or save cancer cells." (PMID 37185406, 2023). "Encouragingly, both lines of the cancer cells were not able to restart their outgrowth during the entire co-culture period (72 h) with the CD28-OX-40-CAR-T/NK cells." (PMID 37761005, 2023). "CAR comprises an extracellular, cancer-specific antibody fused with the intracellular signaling activation domains of CD3 and co-activation ligands, such as CD28 or 4-1BB, which provide engineered T cells with an MHC‐independent mechanism through which to kill cancer cells directly." (PMID 37259079, 2023). "Previous studies have demonstrated that CD28‐CAR‐T cells were more potent in killing cancer cells, as well as 4‐1BB‐CAR‐T cells exhibited lower depletion rates and longer‐lasting killing effects on cancer cells." (PMID 35289077, 2022). "Type 1 conventional CD103+ migrating DCs are antigen-presenting cells (APCs) that elucidate CTLs before cancer cell detection via three different mechanisms: cancer antigen adhered to MHC-I, co-stimulatory molecules (CD80/86 and CD28/152), and pro-inflammatory cytokines (IL-12 and TNF-α)." (PMID 36560420, 2022). "Consistent with previous reports, patients with cancer showed immune exhaustion phenotype as indicated by increased cell-surface expression of PD-1, TIGIT, and Tim-3 but reduced CD28 expression on CD8+ T cells and Vγ9Vδ2+ T cells, while cell surface CTLA-4 was barely detectable." (PMID 35318258, 2022). "Subject headings and keywords such as “CD8+ T cell”, “immunosenescence”, “inflammaging”, “infectious diseases”, “autoimmune disease”, “cancer”, and specific viruses such as “HIV”, “CMV”, “Sars-CoV-2” and specific markers such as “CD28”, “CD57”, were combined in the search." (PMID 35328795, 2022). "The chimeric antigen receptor (CAR) structure consists of a single-chain variable fragment derived from a monoclonal antibody targeting a cancer-specific antigen, intracellular segment, signaling domain derived from TCR, and one or more co-stimulatory sequences (CD28, OX40, or 4-1BB)." (PMID 36125617, 2022). "Together, these data indicate that CD226 expression, but not CD28 expression, is a correlate of anti-PD-L1 response in cancer." (PMID 35263569, 2022). "We found that in some cancers, especially in LUAD and TGCT, FH expression was significantly correlated with multiple immune checkpoint markers, such as BTLA, TNFRSF14, LAIR1, CD48, and CD28." (PMID 34737838, 2021).
cancer (continued). "We discovered patients had higher CD4+CD28+/CD4+ percentage and CD4+CD28+ T cell counts than those in controls, which might imply that CD4+ T cells were activated in cancer occurrence." (PMID 34488711, 2021). "In cancer, wherein senescent cells impact the immune response, further studies are warranted to examine the anergic, activation and exhausted phenotype compared to CD8+CD28− Tregs." (PMID 34831195, 2021). "A lack of durable anti-cancer activity can be caused by CAR T cell exhaustion, which is preferentially observed in CAR T cells with CD28 co-stimulation after repeated antigen-encounter." (PMID 33801448, 2021). "LncRNA TSPOAP1-AS1 showed a significant correlation with the immune-related gene BTLA in 15 kinds of cancers, with a strong correlation in PAAD and CHOL (|r| > 0.8), and the other mainly significant immune genes included CD28 (in 18 types of cancer) and CD40LG (in 14 types of cancer)." (PMID 34195204, 2021). "Also of notice, a pronounced number of critical immunomodulators, which were described in an immunogenomic analysis of major TCGA cancer data sets and included PDCD1LG2, BTN3A2, GZMA, BTLA, CD28, ICOS, and IDO1, were contained in the 358 DEG set." (PMID 32603365, 2020). "Notably, for the T cells from aged cancer patients, our SBCS system produced a 2-fold greater expansion than that obtained by conventional CD3/CD28 antibodies after 14-day stimulation." (PMID 32526703, 2020). "Thus, anti-CD3/CD28 antibody activation and signaling through T cells augments the percentages of CD8+ T cells moderately, and the levels of expansion are less by cancer patients’ CD8+ T cells when compared to CD8+ T cells expanded from healthy individuals." (PMID 33230147, 2020). "Considering the different affinity of CD86 and CD80 for CD28 and CTLA-4, respectively, and the constitutive expression of CTLA-4 in Treg cells, cancer cells could induce antigen tolerance towards themselves by modulating Treg cell functions." (PMID 30123257, 2018). "For example, CD28, CD40, and TNFRSF4 (OX40) antagonists are in early stage clinical trials for treatment of various immune disorders, whereas CD28, CD40, and TNFRSF4 (OX40) agonists are in early stage clinical trials for various cancer indications." (PMID 28822103, 2018). "Notably, the analysis highlighted different T-cell activation pathways in different cancer types, particularly the CTLA4, CD28 and iCOS-iCOSL signalling pathways in T cells, which are the key pathways in anti-CTLA-4 immunotherapy treatments." (PMID 26634437, 2015). "The proportion of CD28+CD57- cells was lower among the cancer patients than the controls at all time-points, though not significantly at one month." (PMID 26711627, 2015). "The other common MS genes, including CD28, KISS1, NME2, BRMS1, shared in over 10 cancer types." (PMID 26486520, 2015). "While cancer cell-intrinsic CD28 facilitates immune escape by functioning as a non-classical RNA-binding protein to stabilize CD274 (PD-L1) mRNA, inhibiting this pathway in cancer cells without impairing essential T cell CD28 costimulation remains a major structural challenge." (PMID 42261788, 2026). "To selectively activate and expand naive CD8+ cells targeting defined viral or cancer epitopes, we developed a unique protein architecture, termed Immuno-STAT, which delivers cognate peptide-specific T cell receptor (TCR) activation alone or in combination with CD28 costimulation." (PMID 40762498, 2025). "To overcome these limitations, we developed Immuno-STAT (IST), a dimeric protein scaffold that delivers peptide-specific T cell receptor (TCR) activation with or without CD28 costimulatory signals to expand CD8+ T cells specific for defined viral or cancer epitopes." (PMID 40762498, 2025). "CD64/CD28/CD3ζ T cells could significantly impact the rational design of personalized studies to treat CRC and SCCHN and the identification of novel FcγR ALs in cancer and healthy cells." (PMID 39962623, 2025).
cancer (continued). "In the TCGA cohort, individuals with higher CD28 and individuals with higher FLT3LG expression had higher survival than those with lower CD28 expression and those with lower FLT3LG expression, showing that less immunosuppressed individuals were better able to combat cancer." (PMID 39672307, 2024). "Based on our findings that AIF-1 expression is positively correlated with the expression of CD28, CD84, CD86, and LAIRI in several cancer types, we hypothesize that further investigation into the potential association between AIF-1 and these immune regulators would be promising." (PMID 37014322, 2023). "In vitro coculture of control HPAF-II cancer cells with nonadherent human PBMCs significantly suppressed the CD3/CD28-induced proliferation of both CD8 and CD4 T cells, and also reduced levels of IFNγ and GMCSF, cytokines important in generating an active antitumor immune response." (PMID 36922934, 2022). "The requirement for CD28 in PD-1 mediated inhibition of T cell activation also suggests eIF3-mediated control of TCR expression may affect PD-1 checkpoint blockade-based cancer immunotherapy." (PMID 34970966, 2021). "Although BTLA and PDL1 employ distinct phosphatases to suppress T-cell signaling, both of them dampen the TCR and CD28 signaling pathways equally, and thus the inhibitors of both BTLA and PDL1 might be regarded as a combination of immunotherapeutic agents for cancer treatment." (PMID 35127742, 2021). "Compared with the traditional method using immobilized CD3/CD28 antibodies, the SBCS system produced approximately 1.5-fold greater expansion of T cells from healthy donors, and more than 2-fold greater expansion of T cells from aged cancer patients after stimulation." (PMID 32526703, 2020). "The findings demonstrated that the PD1/CD28 CSR could enhance the phosphorylation of crucial signaling molecules, such as ERK and Akt, thereby profoundly impacting CTL stimulation, proliferation, and cytokine secretion—fundamental processes for an effective immune response against cancer cells." (PMID 38666913, 2024). "The absence of CD28 expression on CD8 + TEMRA possibly indicates weak T cell receptor engagement, suggesting weaker protective effects against infection and cancer development." (PMID 38755605, 2024). "Of relevance, we demonstrate that the absence of CD28 provides a functional advantage to Ag-experienced (ICOS+, CD137+, CD11ahigh) PD1+CD8+ T cells in the setting of peripheral blood of cancer patients." (PMID 37898752, 2023). "As the numerically dominant Treg population in the tumor microenvironment (TME), CD4+CD25+Foxp3+ cells have been extensively studied in cancers, unlike CD8+CD28− Tregs." (PMID 34831195, 2021). "At the same time, we also found that there were high expression of PD-1 and CD28, and low expression of CTLA-4 on T cells in cancer tissues and in distal nontumor tissues." (PMID 28061450, 2017). "Negative and statistically significant correlations between CD28 expression and percentages of CD4+NKG2D+ T cells were observed in both cancer patients (Spearman ρ = -0.859; p < 0.001) and healthy controls (Spearman ρ = -0.522; p = 0.003)." (PMID 26486970, 2015). "These tri-specific constructs could represent innovative tools for cancer therapies as no similar constructs have been yet approved by FDA for clinical use, even though some are in clinical trials with the format TAA/CD3/CD28." (PMID 39929828, 2025). "To determine if MDSCs inhibit the activity of T cells, we purified MDSCs from one healthy donor and two patients with stage IV cancer and cocultured them with or without CFSE-labeled autologous CD3+ T cells at the 1∶2 ratios in the absence or presence of CD3/CD28 antibody stimulation for 3 days." (PMID 23437326, 2013).
cancer (continued). "The CD4+ T cells obtained from two different healthy donors were polyclonally stimulated with anti-CD3/CD28/CD2 moAb-coated beads and with IL-2 for 12 days, then subsequently polyclonally restimulated for next 3 days without IL-2 in the presence or without MDA-MB-231 cancer cells." (PMID 34439305, 2021).
infection (208 papers, 2004 to 2026). The state of being infected such as from the introduction of a foreign agent such as serum, vaccine, antigenic substance or organism. "The functionality of that cellular response seems to be dependent on T cells, as CD28 KO mice displayed reduced numbers of GC B cells and plasmablasts, and an ensuing higher susceptibility to wild-type (WT) Spz infection." (PMID 38650939, 2024). "To attenuate the cytokine storm underlying infection pathology, yet preserve host defenses, we uniquely targeted the engagement of CD28 with its B7 co-ligands by means of short peptide mimetics of the human CD28 and B7 receptor homodimer interfaces." (PMID 39456976, 2024). "On the other hand, infection with cytomegalovirus (HHV-5) has been strongly implicated in premature immunosenescence by causing expansion of late-differentiated CD8+CD28- T cells." (PMID 33547621, 2021). "It was observed that CD28-deficient mice infected with the Tulahuen strain of T. cruzi had increased susceptibility to the infection." (PMID 30405039, 2018). "Cell fractionation showed that pH1N1 infection caused increased accumulation of CD28 and Zap-70 proteins in plasma membrane in J1.1 cells." (PMID 26848681, 2016). "Of note, after recovery of the patients, the percentage of CD4+CD11b+ and CD4+CD28− declined, indicative of a causal relationship between infection and T cell activation." (PMID 21151520, 2010). "Since the CD28KO mice were unable to clear the virus within 2 weeks after infection, a longer period was studied to see whether CD28-deficiency results in a similar fate on the otherwise resistant C57BL/6 background." (PMID 37090733, 2023). "Hence, the requirement of CD28 costimulation in driving development of humoral immunity seems to depend on parasites causing the infection." (PMID 24516382, 2014). "Therefore, the importance of CD28 costimulation in sustaining CD4+ T cells dependent memory antibody responses seems to be differentially affected by parasite causing the infection." (PMID 24516382, 2014). "Abrogating CD28 costimulation only during secondary infection in inducible CD28 deficient mice led to failure in mounting a protective memory response, strongly suggesting that CD28 costimulation is needed for efficient recall of protective immunity to N. brasiliensis." (PMID 24516382, 2014). "Thus, the efficient recognition of Mtb antigens and successful containment of the infection were likely associated with upregulation of CD28, CD69 and other genes of the T cell activation network in the CDC1551-infected rabbit lungs." (PMID 23448601, 2013). "Furthermore, we showed that the loss of CD3ζ and CD28 downregulation was associated with increased expression of cell surface T cell activation markers and inflammatory cytokines, consistent with a pathogenic infection." (PMID 41329000, 2025). "We isolated human PBMCs from healthy donors and stimulated them with CD3/CD28 T-cell activation cocktails for three days, followed by infection using the spin-inoculation method with the pseudotyped HIVGR670 virus harboring an HIV-1 dual-tropic Env." (PMID 40143326, 2025). "Aging often results in decreased expression and function of these molecules—most notably CD28—leading to diminished cytokine production and weakened responses to infection and vaccination." (PMID 41357512, 2025). "The CD80 signaling pathway related to T-cell activation was increased at 6 w after infection, and increased expression of its receptor CD28 on the surfaces of CD4+ and CD8+ T-cells was confirmed by flow cytometry, suggesting an increase in their activation." (PMID 39590301, 2024). "In the liver, CTLA-4 (P = 0.0473), TCR (P = 0.0470), ICOS (P = 0.0382), CD28 (P = 0.0072) and Bcl-2 (P = 0.0462) were upregulated in undernutrition 75% + infection group at the 5th week post-infection." (PMID 38185681, 2024).